PPARG (peroxisome proliferator activated receptor gamma)
Diseases named in the same sentence as PPARG in open-access papers (continued):
Sharing a sentence is not in itself a finding about the gene and the disease.
nonalcoholic fatty liver disease (61 papers, 2012 to 2025). "Preclinical and clinical studies show that PPARγ targets several genes implicated in various forms of chronic liver disease, including nonalcoholic fatty liver disease (NAFLD)." (PMID 37190114, 2023). "The ubiquitin-mediated degradation of PPARγ is associated with nonalcoholic fatty liver disease (NAFLD)." (PMID 38012162, 2023). "PPARγ is a regulator of lipid metabolism in hepatocytes; changes in the expression of this protein have been associated with non-alcoholic fatty liver diseases through the induction of lipogenic factors." (PMID 34439537, 2021). "The protein levels of TWIST1, TWIST2 and PPARγ were determined in the serum of nonalcoholic fatty liver disease (NAFLD) patients and healthy controls by enzyme-linked immunosorbent assay (ELISA)." (PMID 33879188, 2021). "In Ob/Ob and lipoatrophic mice, elevated expression of PPARγ2 is associated with non-alcoholic fatty liver disease (NAFLD) while inhibition of PPARγ expression reduces hepatic steatosis through downregulation of lipogenesis and inhibition of LD formation." (PMID 26083030, 2015). "Among the SNPs rs10865710 (C-681G), rs7649970 (C-689T), and rs1801282 (C34G, Pro12Ala), the G allele of rs10865710 in the PPARγ gene is frequently observed and has been shown to be associated with increased susceptibility to nonalcoholic fatty liver disease (NAFLD)." (PMID 28042289, 2016). "This study identifies stachyose (STA), a natural oligosaccharide, as a novel partial PPARγ agonist with superior therapeutic efficacy over rosiglitazone in non‐alcoholic fatty liver disease (NAFLD)." (PMID 40994455, 2025). "Peroxisome proliferator‐activated receptor gamma (PPARγ) is a critical therapeutic target for metabolic disorders like non‐alcoholic fatty liver disease (NAFLD)." (PMID 40994455, 2025). "In non-alcoholic fatty liver disease, upregulation of PPARγ expression significantly inhibited saturated fatty acids-induced NF-κB activation and resulted in macrophage polarization into an M2 phenotype." (PMID 36497185, 2022). "In patients with nonalcoholic fatty liver disease (NAFLD), single nucleotide polymorphisms in the circadian gene CLOCK (rs1801260) and PPARγ (rs3856806) are highly prevalent." (PMID 32093272, 2020). "Other studies have reported a positive correlation between increased PPARγ expression and the development of hepatosteatosis and accumulation of hepatic triglycerides in murine models of nonalcoholic fatty liver disease." (PMID 31295333, 2019). "This is in line with clinical studies, in which PPARγ was upregulated in the livers of obese patients with nonalcoholic fatty liver disease (NALFD)." (PMID 22675337, 2012). "Besides, the activation of PPARγ promotes the polarization of M2-type macrophages to prevent the development of non-alcoholic fatty liver disease and liver injury." (PMID 37501214, 2023). "STRING analysis revealed that the altered proteins (AMPK-α, C/EBPα, SREBP-1c, and PPARγ) are mapped into a core network, which was primarily associated with two pathways: nonalcoholic fatty liver disease (NAFLD) pathway (C/EBPα, SREBP-1c, AMPKα) and AMPK signaling pathway (SREBP-1c, PPARγ, AMPKα)." (PMID 31569521, 2019). "Thus, curcumin may prevent nonalcoholic steatohepatitis (NASH)/cirrhosis and nonalcoholic fatty liver disease through direct/indirect induction of PPARγ expression." (PMID 36092543, 2022). "This technology has been used to silence genes crucial for adipocyte differentiation, such as PPARG and FKBP5, as well as to target three genes (SOCS3, DUSP1, and SIK1) that are upregulated in the adipose tissue of patients with nonalcoholic fatty liver disease (NAFLD)." (PMID 39684387, 2024). "Furthermore, there are studies that demonstrate that DHM targeted 14 potential genes in NAFLD, and PPARG and CASP3 were two hub genes for DHM against Non-alcohol fatty liver disease (NAFLD) in high-fat diet (HFD) rats." (PMID 38275711, 2024).
nonalcoholic fatty liver disease (continued). "Western blot revealed that PP1 inhibited the lipid accumulation and fatty acid synthesis in 3T3-L1 adipocytes in two pathways, primarily: nonalcoholic fatty liver disease (NAFLD) pathway (C/EBPα, SREBP-1c, AMPKα) and AMPK signaling pathway (SREBP-1c, PPARγ, AMPKα)." (PMID 31569521, 2019).
pancreatic cancer (60 papers, 2002 to 2025). "The inhibition of this interaction was mediated by the nuclear receptor PPARγ, which was highly expressed in pancreatic tumors and was associated with poor clinical outcomes." (PMID 37189782, 2023). "To detect the mechanisms underlying the role of PPARγ on pancreatic cancer cell survival, we determined the early stage of apoptosis by JC-1 assay in the presence or absence of Rosiglitazone or T0070907." (PMID 35186942, 2021). "Recently, it has been discovered that PPARγ is closely linked to digestive system tumors, as it is overexpressed in esophageal cancer, gastrointestinal cancer, liver cancer, pancreatic cancer, and para-carcinoma tissues." (PMID 29483923, 2018). "This study is the first to describe the effects of PSF on pancreatic cancer cell growth and autophagy associated with PPARγ." (PMID 26309807, 2015). "Among the interaction partners of the markers, more than one-third has been previously reported as associated with survival or prognosis in pancreatic cancer, including PPARG, MUC4, and SMAD3." (PMID 22615549, 2012). "Since PPARγ is also increased significantly in obese patients due to increased adipose tissue, the risk for pancreatic carcinoma is increased." (PMID 23202913, 2012). "For example, PPARγ was found highly expressed in ovarian carcinoma and its overexpression in pancreatic carcinoma was associated with poor prognosis." (PMID 17767717, 2007). "Studies have shown that rosiglitazone-induced radiosensitivity in pancreatic cancer is achieved by increasing the expression and nuclear translocation of PPARγ, which is related to the abnormal lipid metabolism caused by the PPARγ-induced upregulation of FABP4." (PMID 40002387, 2025). "PPARγ is a transcription suppression target of the TGFβ signaling pathway in diverse tissues and deregulation of this pathway as a result of Smad4 mutations may lead to PPARγ upregulation in pancreatic carcinomas." (PMID 23049538, 2012). "Previous evidence indicates that PPARγ signaling can influence chemosensitivity in biliary and pancreatic cancers." (PMID 41403929, 2025). "In SMR analyses, ABCC8/KCNJ11, DPP4, PPARG, ETFDH, and PRKAB1 were associated with anal carcinoma, cardia cancer, and pancreatic cancer." (PMID 38504335, 2024). "The rest of the list expands to high expression of TRPV2 (Transient Receptor Potential Vanilloid 2) in cancerous skin cells, RXRB (Retinoid X Receptor Beta) in bone, and PPARG (Peroxisome Proliferator-Activated Receptor Gamma) in pancreatic cancer." (PMID 39766077, 2024). "Consistent with this possibility, inhibiting MMP2 activity has been considered as a PPARγ‐independent mechanism for thiazolidinediones to reduce invasiveness of pancreatic cancer cells." (PMID 39636301, 2024). "Our findings demonstrate a significant prognostic difference in patients with high PPARG expression levels in both liver and pancreatic cancers." (PMID 38044948, 2023). "It has been reported that ALDH1A3 activates the PI3K/AKT/mTOR signaling pathway by cross‐talking with the transcription factor PPARγ in pancreatic cancer." (PMID 37551838, 2023). "Contrastingly, no discernible differences in the immune cell composition were observed between the patients with pancreatic cancer with high and low PPARG expression." (PMID 38044948, 2023). "Conversely, PPARG exhibited high expression in pancreatic cancer (PAAD), rectum adenocarcinoma (READ), and COAD." (PMID 38044948, 2023). "Modulation of the plasminogen activator system has been proposed to be one metastasis inhibiting mechanism of PPARγ activation in pancreatic cancer." (PMID 35954274, 2022). "Two previously published datasets from Oncomine were initially analyzed to determine the expression pattern of PPARγ in pancreatic cancer and normal tissues." (PMID 35186942, 2021). "Our study found that high expression of nuclear PPARγ in pancreatic cancer tissues was correlated positively with tumor size and predicted poor prognosis in patients." (PMID 35186942, 2021).
pancreatic cancer (continued). "In our future study, we will explore the mechanisms of specific interaction between PPARγ, mitophagy and pancreatic cancer stemness." (PMID 35186942, 2021). "Firstly, the mRNA and protein expression levels of PPARγ were detected in different human pancreatic cancer cell lines." (PMID 35186942, 2021). "PPARγ is expressed in normal pancreas, pancreatic cancer, and para-carcinoma tissues and is highly expressed in pancreatic cancer tissue cells." (PMID 29483923, 2018). "Together, these data argued against the involvement of PPARγ as an E3 ligase in facilitating T315-mediated MUC1-C degradation in these pancreatic cancer cells." (PMID 28692035, 2017). "This study was performed to investigate the in vitro and in vivo effects of TGZ against pancreatic cancer cell lines, as well as its action mechanisms in terms of PPARγ dependency and the Akt and mitogen-activated protein kinase (MAPK) pathways." (PMID 28673319, 2017). "In pancreatic cancer cells, PPARγ activation by PPARγ agonists suppressed STAT3 expression through transcriptional repression to inhibit cell growth." (PMID 27483249, 2016). "This discrepancy along with PPARγ-independent tumor suppressive roles of PPARγ ligands prompted the possibility of an impaired function of PPARγ in pancreatic cancer." (PMID 26820738, 2016). "In this study, we aimed to investigate the relationships between PSF and PPARγ in pancreatic cancer by evaluating the effects of PSF expression in pancreatic cancer cell lines." (PMID 26309807, 2015). "Although several studies implicate PPARγ activation in inhibition of pancreatic cancer cell growth, little is known about the role of PPARβ/δ, save for its role in suppressing inflammation via BCL-6." (PMID 23737761, 2013). "Hes suppresses, among other genes, transcription of PPARγ, neutralizing an anti-inflammatory signal in pancreatic cancer and thus promoting an inflammatory microenvironment." (PMID 23049538, 2012). "Overall, these data argue for a role of PPARγ in pancreatic cancer cell proliferation, differentiation and invasiveness." (PMID 23049538, 2012). "PPARγ activation by troglitazone reduced the proliferation of pancreatic cancer cell lines in vitro and had an additive effect with 9-cis-retinoic acid, a ligand for RXRα." (PMID 23049538, 2012). "The aim of our study was to assess the time-related patterns of variation of PPARγ and DNMTs in pancreatic cancer using in vitro models represented by pancreatic cancer cell lines evaluated after synchronization." (PMID 22966223, 2012). "Pharmacologic inhibition of PPARγ by specific inhibitor T0070907 unexpectedly also reduced pancreatic cancer cells migration in vitro and metastasis formation in an SCID mouse xenograft model in vivo." (PMID 23049538, 2012). "Nuclear receptor Peroxisome Proliferator-Activated Receptor gamma (PPARγ) has a role in many carcinomas and has been found to be overexpressed in pancreatic cancer." (PMID 23049538, 2012). "Peroxisome Proliferator-Activated Receptor gamma (PPARγ) is a nuclear receptor family transcription factor that is expressed in several types of cancers among which gastrointestinal and pancreatic cancers." (PMID 23049538, 2012). "The same team of investigators showed that rosiglitazone- or pioglitazone-induced inhibition of anchorage-independent growth of pancreatic carcinoma cells was PPARγ dependent." (PMID 23049538, 2012). "One gene associated with obesity and diabetes mellitus that has significance in pancreatic carcinoma is PPARγ." (PMID 23202913, 2012). "In pancreatic cancer, MnSOD is upregulated via peroxisome proliferator-activated receptor gamma (PPARγ), which promotes tumor proliferation by suppressing autophagy-related protein 4D (ATG4D)-mediated mitophagy, thus preventing mitochondrial reactive oxygen species (ROS)-induced apoptosis." (PMID 40722952, 2025).
pancreatic cancer (continued). "PPARG was associated with anal carcinoma (OR: 12.909; 95% CI: 3.217–51.795; P-value = 0.0003), HCC (OR: 36.507; 95% CI: 8.929-149.259; P-value < 0.0001), and pancreatic cancer (OR: 0.110; 95% CI: 0.071–0.172; P-value < 0.0001)." (PMID 38504335, 2024). "Additionally, CTNNB1 had the highest deep deletion rate across pan-cancer at 5%, followed by TGFB1 at 3.6% in head and neck cancer and 2.2% in non-small cell lung cancer, and TNF and PPARG in pancreatic cancer with rates of 3.6% and 1.3%, respectively." (PMID 37033970, 2023). "The PPARG and DNMTs appear interrelated in pancreatic cancer, and this interaction might influence cell phenotype and disease behavior." (PMID 37857015, 2023). "Additionally, the mRNA level of CAP1, EGFR and PPARG were identified with significant downregulation in pancreatic cancer cell lines compared to normal pancreatic cells." (PMID 37857015, 2023). "Meanwhile, the activation of PPARγ might reduce pancreatic cancer cell stemness to improve PDAC chemosensitivity via down-regulating ATG4D." (PMID 35186942, 2021). "In this part, we figured out that PPARγ might regulate mTOR-mediated degradation of ULK1, linked to impaired mitophagy in pancreatic cancer cells." (PMID 35186942, 2021). "To investigate whether the enhanced PDAC proliferation via PPARγ-inhibited mitophagic pathway has effects on stemness of pancreatic cancer cells and chemotherapy sensitivity, we detected the expression of PaCSCs’ markers." (PMID 35186942, 2021). "The weakened ATG4D-mediated mitophagy dominated by PPARγ might play a role in the process of inhibiting pancreatic cancer cell stemness." (PMID 35186942, 2021). "Functional assays demonstrated that PPARγ could promote the proliferation of pancreatic cancer cells in vitro and in vivo." (PMID 35186942, 2021). "Previous studies have shown that PPARγ inhibits cell proliferation through cell cycle arrest at the G1/S checkpoint in hepatic oval cells, human pancreatic carcinoma cells, vascular smooth muscle cells, or induces apoptosis in malignant or non-malignant tissue." (PMID 30089804, 2018). "PPARγ is expressed in a variety of normal tissues and tumor sites, as well as in pancreatic cancer." (PMID 28673319, 2017). "In this study, we aimed to determine the correlation between PSF and PPARγ protein levels in pancreatic cancer cells and to examine the effects of different PSF/PPARγ expression levels on cell proliferation using human pancreatic cancer cell lines expressing varying levels of PSF." (PMID 26309807, 2015). "PPARγ has been investigated in multiple preclinical studies in pancreatic cancer." (PMID 23049538, 2012). "Aim of our study was to assess the periodicity of PPARγ and DNMTs in pancreatic cancer (PC)." (PMID 22966223, 2012). "There exists a reciprocal antagonism of PPARγ towards NF-κB that may be relevant in pancreatic carcinoma cases with increased PPARγ expression." (PMID 23049538, 2012). "Previousstudies have suggested that PPARγ is up-regulated in pancreatic cancer." (PMID 19190780, 2008). "Several studieshave shown that PPARγ agonists, including the natural ligand 15-deoxy-Δ12,14-prostaglandin J2, and thiazolidinedione antidiabetic agents, such as citiglitizoneand rosiglitizone, inhibit growth and induce apoptosis in pancreatic cancer." (PMID 19190780, 2008). "Consequently, it is indicated that PPARγ may provide a new molecular biological marker for the early diagnosis of pancreatic cancer and also offer new ways to reinforce the therapy effect of pancreatic cancer and improve its prognosis." (PMID 29483923, 2018).